CHGA (chromogranin A)
Diseases named in the same sentence as CHGA in open-access papers (continued):
Sharing a sentence is not in itself a finding about the gene and the disease.
neuroendocrine tumors (continued). "Neuroendocrine tumors (NETs) comprise a heterogeneous group of malignancies that express neuropeptides as synaptophysin, chromogranin A (CgA), and specific neuronal enolase (NSE), among others." (PMID 28194370, 2017). "The neuroendocrine glycoprotein chromogranin A is a useful biomarker in humans for neuroendocrine tumors and stress." (PMID 28049540, 2017). "Chromogranin A is a reliable biomarker for diagnosing and monitoring treatment outcome and prognosis in humans suffering from neuroendocrine tumors." (PMID 28049540, 2017). "Neuroendocrine tumours (NETs) are a family of neoplasms that come from neuroendocrine cells and express neural markers, such as synaptophysin or chromogranin A." (PMID 25933800, 2015). "In contrast, SYP and CHGA respectively exhibited a 21- and 854-fold enrichment in neuroendocrine tumor lines compared to PCa models (P < 0.0001, Mann-Whitney U test)." (PMID 25859291, 2015). "Pancreastatin is a split product of chromogranin A and has been shown to be a sensitive marker in neuroendocrine tumors." (PMID 25927667, 2015). "Neuroendocrine tumours (NETs) are a family of neoplasms that arise from neuroendocrine cells and express neural markers, such as synaptophysin or chromogranin A. They are mainly distributed in the gastrointestinal tract." (PMID 25933800, 2015). "Cytological examination demonstrated cohesive groups of plasmacytoid cells staining positively for synaptophysin and chromogranin A, which is suggestive of a neuroendocrine tumor." (PMID 25106541, 2014). "They share uniform histological hallmarks, but in addition to morphology diagnosis of neuroendocrine tumors (NETs) is based on cell-specific markers that can be detected by immunohistochemistry (i.e., chromogranin-A and synaptophysin)." (PMID 24915894, 2014). "Cytological examination of the aspirate from the solid component showed cohesive groups of plasmacytoid cells, staining positively for synaptophysin and chromogranin A, which are highly specific markers for neuroendocrine tumors." (PMID 25106541, 2014). "The cells often stain weakly positive for the neuroendocrine tumor markers chromogranin A and synaptophysin, at least in focal areas, and simultaneously produce mucin, like colorectal adenocarcinomas." (PMID 23365545, 2013). "In the WHO classification neuroendocrine tumors have been defined as those in which one or more neuroendocrine markers, such as neuro specific enolase, chromogranin A, and/or synaptophysin, are expressed in at least 50% of cancer cells." (PMID 23734899, 2013). "Plasma levels of chromogranin A have been used as a marker for recurrence in patients with midgut neuroendocrine tumors with fairly good sensitivity." (PMID 24171129, 2013). "The diagnosis of a neuroendocrine tumor in this case is based on the immunohistochemical expression of chromogranin A and vimentin." (PMID 22507757, 2012). "All four tumors were endocrinologically inactive, and diagnosed as neuroendocrine tumor with positive immunohistochemical staining for chromogranin A. These patients were followed up annually by endoscopy with biopsies and abdominal CT and US." (PMID 21658277, 2011). "We have previously developed an oncolytic serotype 5 adenovirus (Ad5) with chromogranin-A (CgA) promoter-controlled E1A expression, Ad[CgA-E1A], with the intention to treat neuroendocrine tumors, including carcinoids." (PMID 20111709, 2010). "Serum chromogranin A is the most useful general and prognostic tumour marker available for neuroendocrine tumour (NET) patients." (PMID 18577995, 2008). "Platelet serotonin and chromogranin A are useful biomarkers for detection and follow-up of neuroendocrine tumour." (PMID 16800893, 2006). "Using specific immunoradiometric assays, we evaluated the clinical usefulness of chromogranin A and the α-subunit of glycoprotein hormones in neuroendocrine tumours of neuroectodermic origin." (PMID 11259096, 2001).
neuroendocrine tumors (continued). "Chromogranin A (CgA), a major protein of chromaffin granules, has been described as a potential marker for neuroendocrine tumours." (PMID 10408695, 1999). "Neuroendocrine tumors (NETs) of the small intestine, another important differential diagnosis, are typically chromogranin A and synaptophysin positive and may present with obstruction, anemia, or abdominal pain." (PMID 41302109, 2025). "Moreover, chromogranin A levels are more frequently elevated in well-differentiated than in poorly differentiated neuroendocrine tumors." (PMID 40445313, 2025). "Elevated chromogranin A and biopsy confirmed a grade 1 neuroendocrine tumor." (PMID 41181755, 2025). "Furthermore, immunohistochemical markers, such as neuron-specific enolase, chromogranin A, and synaptophysin, are used for their high sensitivity in the diagnosis of neuroendocrine tumors." (PMID 40141766, 2025). "With the help of immunohistochemistry, the histopathological finding of the specimen confirmed the diagnosis of multiple neuroendocrine tumors with positive expression of neuron-specific enolase, synaptophysin and chromogranin A. Subsequently, the patient received distal gastrectomy." (PMID 40406402, 2025). "Currently, Chromogranin A is established as a circulating biomarker for Neuroendocrine Neoplasms." (PMID 37318593, 2023). "Chromogranin A (CgA) is a well-known biomarker for neuroendocrine tumors (NETs)." (PMID 37954718, 2023). "Before circulating biomarker measurements, all PanNEN patients displayed normal routine lab tests, including alkaline phosphatase, ALT/AST, calcium, or phosphate levels, and neuroendocrine tumor marker levels (chromogranin A, serotonin and 5-hydroxyindole acetic acid)." (PMID 37510802, 2023). "Also, as a neuroendocrine tumor, the production of chromogranin A is present, for that reason elevation of this marker is related to neuroendocrine mass because this enzyme comprises 40% of the production of the chromaffin cells." (PMID 34352621, 2021). "Chromogranin A, a secretory protein, is a well-established biomarker for neuroendocrine tumors." (PMID 34685446, 2021). "Chromogranin A (CgA), synaptophysin (Syn) and the Ki-67 index play significant roles in diagnosis or the evaluation of the proliferative activity of gastroenteropancreatic neuroendocrine neoplasms (GEP-NENs)." (PMID 32917216, 2020). "Parathyroid secretory protein 1 is a representative protein which serves as a precursor for peptides with distinct bioactive function, presently, chromogranin A being used as marker for neuroendocrine tumors." (PMID 31963795, 2020). "Until 2003, a breast cancer could be classified as a primary neuroendocrine tumor when expressing chromogranin A, chromogranin B, or synaptophysin in more than 50% of the total cell population." (PMID 33584543, 2020). "First, some biochemical markers such as chromogranin A (CgA) and neuron-specific enolase (NSE) maybe useful diagnostic biomarker for neuroendocrine tumor." (PMID 30847618, 2019). "As CHGA peptides are produced by a variety of endocrine cell types, the combined analysis of peptides derived from proglucagon and CHGA could potentially be used to help distinguish a glucagonoma from other types of neuroendocrine tumour." (PMID 29857350, 2018). "Human Chromogranin A (CgA), a 439-residue-long protein present in the secretory granules of many normal and neoplastic neuroendocrine cells, currently represents the main biomarker for neuroendocrine neoplasms (NENs)." (PMID 29723285, 2018). "For neuroendocrine tumours, the panel should include synaptophysin, chromogranin A, and CD56." (PMID 29808414, 2018). "Neuroendocrine tumour cells are constantly secreting chromogranin A into the supernatant." (PMID 25754106, 2015).
neuroendocrine tumors (continued). "In the present study, the results of the microscopic examination were consistent with the features of a neuroendocrine neoplasm, and the immunohistochemical staining was positive for glucagon, synaptophysin and chromogranin A. These findings confirmed the diagnosis of a glucagonoma." (PMID 25789004, 2015). "In this study, we investigated whether NPS or NPSR1 might be used as biomarker for NET in a wide panel of neuroendocrine tumors, characterized by assessing the Ki-67 proliferation index and chromogranin-A and synaptophysin expression." (PMID 24915894, 2014). "Chromogranin A is the most important biomarker for diagnosis of classic neuroendocrine tumors." (PMID 23365545, 2013). "Chromogranin A (CgA), a secretory protein involved in neural cell adhesion and expressed by many neuroendocrine cells, has also been recognized as a useful tissue and serum marker of neuroendocrine tumors." (PMID 26316932, 2011). "We investigated whether plasma chromogranin A (CgA), measured by a new immunoradiometric assay, may be a sensitive and specific marker of phaeochromocytoma and of other neuroendocrine tumours." (PMID 11237384, 2001). "Among the non-specific markers, chromogranin A is associated with well-differentiated neuroendocrine tumors, neuron-specific enolase serves as a marker for poorly differentiated tumors, and pancreatic polypeptide is often elevated in non-functioning pancreatic neoplasms." (PMID 41567922, 2025). "CHGA, known as Chromogranin A (CgA), a protein stored in the secretory granules of many neuroendocrine cells and neurons, could be detected in the blood of patients with neuroendocrine tumors or heart failure CHGA could also be detected in the serum of some HCC patients." (PMID 36712870, 2022). "Finally, SCLCs and large cell neuroendocrine carcinoma (LCNEC) are neuroendocrine tumors (NETs) that usually have neuroendocrine differentiation properties and are defined by the specific expression of chromogranin A (CHGA), synaptophysin (SYP), and neural cell adhesion molecule 1 (NCAM1)." (PMID 35962452, 2022). "Three non-secretory atypical carcinoid tumors (i.e., no production of serotonin or ACTH) with low chromogranin A levels were found to have detectable expression of genes that have been linked to neuroendocrine tumor pathobiology in the circulating blood using the NETest." (PMID 33641055, 2021). "The aim of this prospective study was to examine whether discontinuation of proton pump inhibitors (PPIs) or replacement by H2-receptor antagonists (H2RA) resulted in a decrease of chromogranin A (CgA) levels in 196 patients with well-differentiated neuroendocrine tumours (NETs)." (PMID 21989216, 2011). "Chromogranin A (CGA) is a peptide secreted by endocrine and neuroendocrine cells, filtered by the glomerulus, and secreted in excess by neuroendocrine neoplasms." (PMID 41527631, 2025). "Tumor cells in SCCOPT are generally positive for immunohistochemical neuroendocrine markers such as chromogranin A, synaptophysin, and CD56, demonstrating that SCCOPT represents a true neuroendocrine tumor." (PMID 40091949, 2025). "Biochemical evaluation, including serum chromogranin A and 24-hour urinary 5-hydroxyindoleacetic acid (5-HIAA), is recommended to support the suspicion of a neuroendocrine tumor and to monitor disease progression." (PMID 41181755, 2025). "Neuroendocrine tumors expressing markers like SOX2, Synaptophysin, and Chromogranin A generally exhibit high aggressiveness and poor prognosis." (PMID 40735045, 2025). "The chief tumor cells were positive for chromogranin A, synaptophysin, and CD56 antibodies, indicating a neuroendocrine tumor." (PMID 38721148, 2024). "Immunohistochemical markers such as chromogranin A, synaptophysin, and CD56 are neuroendocrine tumors’ most common positive markers." (PMID 39292386, 2024).
neuroendocrine tumors (continued). "Pathological examinations showed that the bilateral breast masses were also positive for immunohistochemical staining of chromogranin A, synaptophysin, and CD56, leading to a diagnosis of bilateral breast metastasis of neuroendocrine tumor." (PMID 39292386, 2024). "Widely recognized as a major marker of neuroendocrine tumor (NET), chromogranin A (CgA) has been found to be related to the clinical deterioration and higher risk of mortality in patients with AHF and CHF." (PMID 37298029, 2023). "Among these, SCGN, CHGA and CADM1 are known neuroendocrine tumor markers, suggesting this proteotype is neuroendocrine-like." (PMID 35383171, 2022). "Furthermore, traditional neuroendocrine tumor markers like chromogranin A and other novel biomarkers should also be included in a future confirmatory study and thus could potentially increase the diagnostic sensitivity in combination with cfDNA integrity and hypomethylation." (PMID 35205773, 2022). "In contrast, UWG01CTC, isolated from a patient with neuroendocrine tumour, showed variable and weak cytokeratin (Cam5.2) immunostaining, with strong expression of neuroendocrine markers (CD56+, synaptophysin+, chromogranin A+)." (PMID 31953491, 2020). "This work discusses the clinical performance of chromogranin A (CGA), a commonly measured marker in neuroendocrine neoplasms, for the diagnosis of pheochromocytoma/paraganglioma (PPGL)." (PMID 31027285, 2019). "Immunohistochemically, grade 2 NETs are diffuse and positive for synaptophysin (Syn), chromogranin A (Cg A) and CD56, and the Ki-67 proliferation index indicates the malignant characteristics of neuroendocrine tumors." (PMID 31228945, 2019). "Neuroendocrine tumors of the esophagus more frequently present in the middle of the esophagus and stain positive for CD56, synaptophysin, and chromogranin A." (PMID 30139375, 2018). "Immunohistochemically, NETs are positively stained by one or more neuroendocrine markers, and chromogranin A, synaptophysin, CD57, CD56, neuron specific enolase, and neurofilaments are important for evaluating neuroendocrine neoplasms." (PMID 27840746, 2016). "Eight genes (CHGA, CPE, ENO2, INSM1, PTPRN2, SERPINA10, and SLC18A1/2) that have been previously identified as markers of neuroendocrine tumors were confirmed in this study to be altered." (PMID 21853033, 2011). "We incorporated immunostaining for thyroid transcription factor-1, chromogranin A, and synaptophysin, which yielded negative results, consequently excluding the possibility of high-grade neuroendocrine tumors." (PMID 40851880, 2025). "Current biochemical markers, including plasma or urinary metanephrines and chromogranin A, a blood non-specific neuroendocrine tumour marker, have limitations, especially in biochemically negative tumours." (PMID 41026309, 2025). "One example is chromogranin A (CHGA), which is a marker of neuroendocrine tumors." (PMID 40869264, 2025). "Neuroendocrine markers like CD56, Chromogranin A (CgA), and Synaptophysin (Syn) are usually negative in PH, aiding in its distinction from neuroendocrine tumors despite potential histological similarities." (PMID 39228982, 2024). "The concentrations of selected specific and nonspecific markers of neuroendocrine neoplasms, such as chromogranin A, serotonin, and 5-hydroxyindoleacetic acid, were also assessed in patients with NEN." (PMID 35372578, 2022). "Fragments of chromogranin A (CHGA), an acidic glycoprotein frequently used as a prognostic factor for many neuroendocrine tumours, can affect critical components of the TME, such as fibroblasts and endothelial cells, as well as tumour progression and immunotherapy in patients." (PMID 35936012, 2022).
neuroendocrine tumors (continued). "The combination of hematoxylin and eosin staining, Ki-67, and immunostaining of classic neuroendocrine markers, such as chromogranin A, CD56, and synaptophysin, are normally used to diagnose high-grade neuroendocrine tumors; however, they are frequently heterogeneous." (PMID 34829292, 2021). "Since SCLC is classified with neuroendocrine tumors, immunohistochemistry is very important in the diagnosis of SCLC, especially some neuroendocrine markers, such as Synaptophysin (Syn), Chromogranin A (CgA) and CD56 (an alias for neural cell adhesion molecule 1)." (PMID 34168983, 2021). "Meanwhile, TCACC is negative for neuroendocrine markers, such as chromogranin A and synaptophysin, and this immunohistochemical feature is useful in ruling out neuroendocrine tumors." (PMID 32756201, 2020). "The dosage of chromogranin-A should be assessed annually for follow-up, but this marker is found to be 60–80% higher in patients with neuroendocrine tumors, regardless of the primary site." (PMID 29324681, 2018). "One commonly used protein marker is chromogranin A (CgA), which is elevated and particularly useful in patients with non-functioning neuroendocrine tumors as well as in its ability to indicate poorer prognosis." (PMID 30250431, 2018). "Pathological analysis of the resected submucosal 1.8 cm tumour of the Meckel diverticulum and a metastatic local lymph node confirmed a well differentiated neuroendocrine tumour (grade I), whereas immunohistochemistry was positive for ACTH, chromogranin A and synaptophysin." (PMID 26610855, 2015). "Negative chromogranin A staining also makes a neuroendocrine tumor with clear cell features less likely in this case." (PMID 24955270, 2014). "The negative staining of synaptophysin and chromogranin A ruled out neuroendocrine tumors." (PMID 41515615, 2026). "The non-specific marker of neuroendocrine tumors is chromogranin A (CgA)." (PMID 41007858, 2025). "While synaptophysin may be positive, especially in differentiating neuroendocrine tumors, chromogranin A (n = 2) is usually negative in SPN." (PMID 37733117, 2023). "Insulinoma-associated protein 1 (INSM1) has been considered as a novel immunostaining marker for neuroendocrine tumors (NETs) and is hypothesized to be more reliable than first-generation NET biomarkers, such as CGA (chromogranin A), SYP (synaptophysin), and CD56 (neural cell adhesion molecule)." (PMID 36531655, 2022). "Chromogranin A (CgA) is a non-specific biomarker excreted by neuroendocrine tumor (NET) cells." (PMID 34868938, 2021). "Unfortunately, these markers are not always present in neuroendocrine tumors, and non-neuroendocrine tumors may also occasionally express Chromogranin A or Synaptophysin—making the diagnosis difficult to make for certain cases." (PMID 34571751, 2021). "Furthermore, immunohistochemical findings showed an overexpression of synaptophysin and chromogranin A, indicative of a neuroendocrine tumor such as NEN or NEC, and not an adenocarcinoma." (PMID 32592083, 2020). "All patients in our study were positive for CD56 and synaptophysin and most were negative for chromogranin A. These findings could have resulted in an incorrect diagnosis of neuroendocrine tumors." (PMID 33097069, 2020). "Besides typical morphology, well-known biomarkers for PCC/PGLs are positive immunohistochemistry for chromogranin A, synaptophysin, and S100; however, this does not allow differentiation from any other neuroendocrine tumors." (PMID 31597347, 2019). "However, the expression of synaptophysin and, to a lesser extent, also chromogranin A is not restricted to the neuroendocrine neoplasms, but may also be in a subset of non-neuroendocrine epithelial and non-epithelial neoplasms." (PMID 34647171, 2022).
neuroendocrine tumors (continued). "Immunohistochemical expression of CD56, synaptophysin, and chromogranin A was strongly positive in the tumor cells, while CD117, CD30, epithelial membrane antigen (EMA), alpha-inhibin, and Oct-4 nuclear stain were negative, consistent with a neuroendocrine tumor." (PMID 24171129, 2013).